PTX3 (pentraxin 3)
Diseases named in the same sentence as PTX3 in open-access papers (continued):
Sharing a sentence is not in itself a finding about the gene and the disease.
tumor (continued). "Interestingly, four genes (TIMP1, SERPINE1, PLAUR and PTX3) associated with poor overall survival of both LUAD and LUSC patients, are involved in the regulation of ECM remodelling, which plays a key role in the aggravation of tumour malignancy and metastasis." (PMID 34807957, 2021). "Therefore, PTX3 promotes tumor progression and its expression can predict survival outcome." (PMID 32984316, 2020). "JUN might affect tumor progression through regulating PTX3 expression." (PMID 32984316, 2020). "However, it remains unknown whether PTX3 plays a protective or promotive role in cancer in that it may impose an important influence on various aspects of cancer such as tumor initiation, angiogenesis, metastasis and immune-regulation." (PMID 33219288, 2020). "Notably, upregulated miR-29c-3p coupled with reduction of its predicted target recombinant pentraxin 3(PTX3) was observed in the same year using whole transcriptome microarray chips, which indicated the level of tumor suppressor PTX3 is inhibited by miR-29c-3p." (PMID 32983987, 2020). "Moreover, PTX3, by recruiting Factor H or inhibiting angiogenesis, can also lead to a reduced inflammatory response, carcinogenesis and angiogenesis in other tumor contexts and in this scenario the binding to C1q could reduce complement activation." (PMID 33110136, 2020). "Therefore, PTX3 promotes tumor progression through negative regulating cells autophagy." (PMID 32984316, 2020). "Whether PTX3 functions as a tumor-suppressor or tumor-promoting factor in HCC requires future work." (PMID 32078718, 2020). "Interestingly, PTX3 has been shown to facilitate the dysregulation of mitogenic signaling pathways and to promote cellular proliferation, angiogenesis, insensitivity to apoptosis, cancer cell invasion and migration, and tumor escape from immunosurveillance." (PMID 33110136, 2020). "In this frame, the study of PTX3 activity in the tumor milieu may represent a prototype of how a deeper analysis of tumor microenvironment, following treatments or modulation of stromal components, may unveil significant effects or add more details on the evolution of tumor populating cells." (PMID 31533326, 2019). "Indeed, the role of PTX3 in neoplastic transformation and growth has been shown to depend on the context and to be influenced by its property to interact with different molecules in the tumor environment." (PMID 31019517, 2019). "In addition, database analysis and immunehistochemical data on tumor samples from BC patients raise the possibility that PTX3 may represent a potential functional biomarker in BC evolution." (PMID 31480336, 2019). "Thus, similar to the results obtained following PTX3 expression in tumor cells, the systemic production of PTX3 in transgenic TgN(Tie2-hPTX3) mice results in a significant inhibition of both tumor cells as well as of different FGF/FGFR-dependent components of tumor microenvironment." (PMID 30443492, 2018). "Moreover, PTX3 accumulation in tumor stroma and bloodstream, obtained through endothelial specific overexpression of PTX3 in transgenic mice, deeply affects the tumorigenic, angiogenic and metastatic potential of various syngeneic FGF-dependent tumor cell lines." (PMID 30443492, 2018). "Moreover, when considering the role of FGF2 in the formation and maintenance of lymphatic vessels, it is possible to hypothesize that PTX3 may inhibit FGF2-mediated lymphangiogenesis and its associated events, including tumor metastatic dissemination." (PMID 30349543, 2018). "However, the mechanism involved in the PTX3-mediated stimulation of tumor-endothelial cell interaction and vessel permeability remains unknown." (PMID 28489600, 2017). "In addition, PTX3 was found to inhibit the growth of various FGF-dependent tumor types." (PMID 29137286, 2017). "However, the correlation between lipid metabolite-triggered tumor metastasis and PTX3 expression remains unclear." (PMID 28489600, 2017).
tumor (continued). "Therefore, PTX3 acts as an extrinsic oncosuppressor in regulating tumor promoting inflammation." (PMID 27377307, 2016). "In addition, EGF-induced PTX3 also enhanced tumor cell-endothelial cell interactions." (PMID 25797258, 2015). "In addition, to study whether EGF-induced PTX3 regulated the distal dissemination of tumor cells, EGF-treated parental and shPTX3 cells were injected into the tail vein of mice." (PMID 25797258, 2015). "Thus, we speculate that EGF-induced PTX3 promoted tumor metastasis by modulating adhesion between tumor and endothelial cells." (PMID 25797258, 2015). "PTX3 exerts antiangiogenic and anticarcinogenic effects, primarily by inhibiting the FGF/FGFR pathway, as well as exerting tumor-suppressing or -promoting effects through other signaling pathways, including NF-κB and PI3K/AKT." (PMID 41479916, 2025). "There was a suggestion of efficacy that tumour shrinkage correlated with potential biomarkers such as CA19-9, Vitamin A levels, serum pentraxin 3 levels (PTX3) as well as tissue retinal binding proteins such as CRABP2 and FABP5." (PMID 39833722, 2025). "Here we identified that MMP9, MMP13, VCAM1, and PTX3 overexpression not only promotes ECM remodelling and angiogenesis but also facilitates tumour infiltration, thereby reconfiguring the TME to favour migration and metastasis." (PMID 41007296, 2025). "The analysis revealed that PTX3 levels were significantly correlated with drinking history, TNM stage, BCLC stage, tumor size, tumor number, and vascular invasion." (PMID 39686456, 2024). "Furthermore, we established a therapeutic model by administering an anti-PTX3 antibody [WHC-001; a neutralizing antibody that binds to PTX3, preventing its interaction with CD44] to evaluate whether blocking PTX3 in the tumor microenvironment can mitigate stroma-mediated tumor growth." (PMID 38243273, 2024). "TMX4, ALPL, PTX3, BHLHE40, TNFRSF12A and CST3 demonstrated significant overexpression in LUSC tumour tissues, whereas CLDN1, VKORC1 and ADD3 exhibited significant underexpression in the HPA database." (PMID 38520221, 2024). "Pentraxin 3 (PTX3) is responsive to proinflammatory cytokines and modulates immunity and tissue remodeling, but its involvement in tumor progression appears to be context-dependent and is unclear." (PMID 38243273, 2024). "Our results demonstrated that coinjection of Ptx3 knockdown MEFs led to a reduction in MC38/MEF tumor growth, suggesting a contribution of PTX3 to stroma-mediated tumor growth." (PMID 38243273, 2024). "Similar to PTX3, CRP contributes to tumor progression by modulating the tumor microenvironment, particularly through angiogenesis and inflammatory responses." (PMID 39594709, 2024). "The contribution of tumor and stromal cells to PTX3 production in TNBC was assessed by analyzing single cell RNA sequencing data and RNAscope performed on TNBC tumor samples." (PMID 37749607, 2023). "The methylation of HOXA1, IGFBP2, PTX3, TIMP1, SHOX2, and SH2D4A decreases with increasing tumor grade." (PMID 37091145, 2023). "PTX3, CCL2, and CXCL12 are stroma-derived factors that increase the proliferation rate of mutant desmoid tumor cells." (PMID 37377751, 2023). "For example, 1,25(OH)2D treatment increased the expression of pentraxin 3 (PTX3), a known pattern recognition molecule and oncosuppressor that inhibits FGF-dependent tumor growth and metastasis." (PMID 37228489, 2023). "PTX3 activates JNK signaling and regulates the epithelial‐to‐mesenchymal transition, which is always accompanied by tumor metastasis." (PMID 37063077, 2023). "A prognostic index for tumor samples could be calculated by the formula: IRGPI = (HTN3 expression * 0.096) + (CTSG expression * −0.152) + (MAPT expression * 0.122) + (CCL28 expression * −0.094) + (PTX3 expression * 0.138) + (SEMA3G expression * −0.140) + (USP2 expression * 0.107)." (PMID 36845378, 2023). "PTX3 is closely related to the expression of PD‐1, PD‐L1, CD276, and HAVCR2 in the tumor microenvironment." (PMID 35855654, 2022).
tumor (continued). "Consistently, PTX3 was more co‐expressed with CD68 and CD163 in tumor tissues than in paratumor tissues." (PMID 35855654, 2022). "PTX3 is a pattern-recognition receptor that acts as an FGF antagonist, blocking the growth and vascularization of FGF-regulated tumor types, including PCa." (PMID 35053442, 2022). "Therefore, PTX-3 could suppress tumor development in FGF-dependent cancers." (PMID 36499628, 2022). "Thus, PTX3 inhibition may synergize with anti-tumor therapies, including mEHT." (PMID 33917524, 2021). "Therefore, PTX3 might promote tumor progression by inhibiting tumor cells autophagy." (PMID 32984316, 2020). "Therefore, PTX3 might able to affect tumor immune landscape." (PMID 32984316, 2020). "Accordingly, the PTX3-derived FGF trap NSC12 acts in vitro and in vivo as a ciliogenic anticancer molecule on FGF-dependent tumor cells." (PMID 32630309, 2020). "Therefore, PTX3 may be a new marker of tumor related inflammation and malignant glioma." (PMID 31957804, 2020). "Accordingly, transgenic PTX3 overexpression impairs efficaciously the activation and signaling of the FGF/FGFR system in FGF-driven tumors, thus affecting tumor growth and metastasis." (PMID 31487962, 2019). "To get further insights about the impact of PTX3 overexpression in MIBC, we took advantage of MB49 cells, a murine model of high-grade BC that allows the growth of tumor cells in a syngeneic and immunocompetent background." (PMID 31480336, 2019). "Like PTX3, NSC12 binds various members of the FGF family and inhibits tumor growth, vascularization, and metastatic capacity in different FGF-dependent tumor models." (PMID 31480336, 2019). "Accordingly, PTX3 overexpression can inhibit FGF-driven epithelial-to-mesenchymal transition (EMT) and tumor/metastatic burden in melanoma models and hampers tumor growth in preclinical models of prostate cancer and fibrosarcoma." (PMID 31480336, 2019). "Moreover, the detection of increased levels of “systemic” PTX3, like in the urines of BC patients, may be the result of the general inflamed milieu generated by and during tumor progression, thus masking the regulatory effect exerted by PTX3 produced by cancer cells." (PMID 31480336, 2019). "PTX3 interacts with FGF2 and other FGF family members, thus acting as a multi-FGF antagonist able to inhibit FGF-dependent neovascularization and tumor growth." (PMID 30443492, 2018). "Accordingly, homozygous PTX3 inactivation in Ptx3−/− mice enhances FGF-dependent angiogenesis, tumor growth and metastasis." (PMID 30443492, 2018). "Recently, the characterization of the molecular bases of FGF2/PTX3 interaction has allowed the identification of NSC12, the first low molecular weight pan-FGF trap able to inhibit FGF-dependent tumor growth and neovascularization." (PMID 30349543, 2018). "In addition, PTX3 administration resulted to be protective in a model of arterial thrombosis, and in carcinogenesis models, it has been demonstrated that PTX3 acts as extrinsic oncosupressor by regulating complement-mediated and macrophage-sustained tumour inflammation." (PMID 28228104, 2017). "Oleate-induced PTX3 enhanced the expression of vimentin and matrix metalloproteinase-3 (MMP-3) to regulate tumor invasion." (PMID 28489600, 2017). "Our results show that the oleate-induced autocrine production of PTX3 enhanced MMP-3 and vimentin expression and tumor/endothelial cell interactions to promote the metastatic seeding of tumor cells in the lungs." (PMID 28489600, 2017). "However, none of these studies linked PTX3 levels with postsurgical tumor relapses." (PMID 26859579, 2016). "The inhibition of this tumor-endothelial cell interaction was rescued when PTX3-knockdown cells were treated with EGF and PTX3." (PMID 25797258, 2015). "Thus, we raised the hypothesis that PTX3 may also participate in tumor migration." (PMID 25797258, 2015).
tumor (continued). "The autocrine production of EGF-induced PTX3 altered the expression of metastatic molecules, such as increasing fibronectin and MMP-9, resulting in enhanced tumor metastasis." (PMID 25797258, 2015). "The soluble pattern recognition receptor long pentraxin-3 (PTX3) binds various FGFs, including FGF2 and FGF8b, thus inhibiting the angiogenic and tumorigenic activity of androgen-regulated tumor cells." (PMID 25912421, 2015). "Accordingly, transgenic PTX3 overexpression efficaciously impairs the activation and signaling of the FGF/FGFR system in FGF-driven tumor cell lines, thus affecting tumor growth and metastasis." (PMID 25912421, 2015). "We next demonstrated that PTX3, a gene that is directly regulated by CEBPD, can fully support the protumor role of CEBPD in the tumor microenvironment." (PMID 26124179, 2015). "In addition, we studied whether PTX3 contributed to EGF-induced tumor invasion." (PMID 25797258, 2015). "Cui’s study reveals that Pentraxin-3 (PTX3) effectively inhibits the stemness of GC cells and modulates the TME by preventing the M2-polarization of macrophages which is known to promote tumor progression and immune evasion." (PMID 40028336, 2025). "Unlike CRP, which is primarily produced in the liver, PTX3 is synthesized by cells within the tumor microenvironment, offering a more accurate reflection of tumor activity." (PMID 39594709, 2024). "The knockout efficiency was examined by measuring the plasma Ptx3 level in both Ptx3fl/fl and Ptx3fl/fl;Ubc-Cre mice, and the results showed that under systemic Ptx3 deletion, MC38 tumor growth was attenuated, suggesting that PTX3 contributes to tumor progression." (PMID 38243273, 2024). "Tumor cells (n=38284; 31.2%, n=8; range 22.5-37.2% per PDAC) were annotated into 7 different subtypes, based on the expression of Pan-Ck, cytokeratin 7 (Ck-7), CD44, S100A4, PTX3, CA-IX, CD74." (PMID 39575252, 2024). "Notably, TMX4, ALPL, PTX3, BHLHE40, TNFRSF12A and CST3 demonstrated significant overexpression in LUSC tumour tissues, whereas CLDN1, VKORC1 and ADD3 exhibited significant underexpression." (PMID 38520221, 2024). "Since the tumour did not invade the bladder muscle, there is a possibility that the tumour was not large enough to have an effect on systemic levels of PTX3." (PMID 38542446, 2024). "In addition to using tamoxifen-induced Ptx3 conditional knockout mice, we established a subcutaneous mixed stroma–tumor model in mice by coinjecting MEFs (high PTX3-expressing stromal cells) and MC38 cells (low PTX3-expressing cancer cells)." (PMID 38243273, 2024). "PTX3 exerts non-redundant functions in various physio-pathological conditions and it has been described to be involved in tumor cell proliferation, angiogenesis, metastatic dissemination and cancer immune-modulation." (PMID 37749607, 2023). "Also, the overexpression of PTX3 significantly increased the percentage of ALDH+ cells and the capacity of MDA-MB-468 PTX3 cells to form tumor-spheres." (PMID 37749607, 2023). "The genes expression levels in the model were detected by qRT-PCR, and the results showed that they were highly expressed in 20 pairs of tumor and normal tissues (UNCX, SLC6A3, AGAP2-AS1, LINC00968, PTX3 and SBSPON), while ITPRID1, DCST2, ETV3L, and ENSG00000261327 were down-regulated." (PMID 36647156, 2023). "Also, in vitro and in vivo data show that PTX3 confers more aggressive biological features to TNBC cells, resulting in augmented tumor cell proliferation and growth." (PMID 37749607, 2023). "In addition, PTX3 expression has been shown to be regulated by PI3K and to foster tumor stem-like features and bad prognosis in basal-like TNBC." (PMID 37749607, 2023). "Taken together, our data suggest that nonmutant stromal fibroblasts induce mutant desmoid tumor cell proliferation via secreting soluble factors, including PTX3 and STAT6 activation." (PMID 37377751, 2023).
tumor (continued). "The tumorigenicity assay indicated an obvious decrease in subcutaneous tumor volumes when ZNF148 was knocked down in t‐DCs, and this effect could be partially reversed by the simultaneous upregulation of PTX3." (PMID 37063077, 2023). "In this frame, our data indicate that PTX3 secreted by tumor cells promotes the activation of the TLR4/IRAK1 pathway in TNBC cells, and that the expression of PTX3 itself may determine the antitumor responses to TLR4 inhibition." (PMID 37749607, 2023). "Finally, in order to investigate if a PTX3/TLR4 autocrine loop of stimulation exists in TNBC cells, the expression of PTX3 in MDA-MB-231 shNT cells and tumor xenografts was assessed after TLR4 inhibition." (PMID 37749607, 2023). "To identify candidate stroma-derived factors that might influence desmoid tumor cell proliferation, we treated mutant-only cultures with recombinant IGFBP3, PTX3, CCL2, CXCL12, and CHI3L1 in serum-free conditions." (PMID 37377751, 2023). "Here, we observed that after PTX3 downregulation in MDA-MB-231 cells the percentage of ALDH+ cells (a functional marker of stem-like cell populations) was significantly reduced, as well as the number and dimensions of tumor-spheres formed." (PMID 37749607, 2023). "Similarly, in early-stage tumor patients, PTX3 levels were higher than controls (**** p < 0.0001), indicating that both LAMC2 and PTX3 are already altered in the earliest stages of PDAC." (PMID 35681634, 2022). "Additionally, our previous studies have also indicated that PTX3 is a downstream target of CEBPD and that the CEBPD/PTX3 axis is involved in some inflammation-related diseases and even in the tumor progression." (PMID 36530573, 2022). "The role of PTX3 in cancer is not clear, and its contribution as a tumour promoter or suppressor is being equally reported." (PMID 36362114, 2022). "In fact, the results specifically indicate that PTX3 plays a role in suppressing the tumour initiation of FGF‐dependent tumours but not PTX3‐elevated cancers." (PMID 35090088, 2022). "We identified five genes (ITGA5, MMP9, PTPRN, PTX3, and STX1A) that could significantly affect the OS rate of patients, and the difference between the tumor group and the normal group was statistically significant." (PMID 33767729, 2021). "Increasing tumor grade, stage, nodal status and presence of metastases did not affect the serum PTX3 levels in those patients with PDAC, although this study was not powered to detect such differences." (PMID 34188166, 2021). "It has been reported that PTX3 tends to be expressed in the stroma rather than in tumor cell components, suggesting that the PTX3 gene is epigenetically modified and silenced in cancer cells." (PMID 34745947, 2021). "Interestingly, PTX3 strongly reduced FGFR1 activation in both sulfobiotin+ endothelial cells and tumor cells as assessed by phospho-FGFR1 immunostaining." (PMID 34066669, 2021). "Accordingly, PTX3 expressing xenografts (+DOXA) showed reduced tumor vascularization (Sulfobiotin+ area) and proliferation (pHH3+area) that resulted in a significant delay of tumor growth when compared to controls (−DOXA)." (PMID 34066669, 2021). "Furthermore, PTX3 was shown to be able to promote HCC progression and high PTX3 expression in tumor tissues was related to unfavorable prognosis in HCC patients." (PMID 33219288, 2020). "Analysis of complement system activation on tumor tissues showed the co-expression of PTX3 with C1q, C3aR, C5R1 and CD59, but not with C5b-9 terminal complex." (PMID 32345771, 2020). "PTX3 is described as an oncosuppressor in mouse models, inhibiting complement activation via FH recruitment, limiting the production of C5a and CCL2 (a pro-inflammatory chemokine) and avoiding the recruitment of tumor-promoting macrophages." (PMID 33113844, 2020).